FBXW7 (F-box and WD repeat domain containing 7)
Diseases named in the same sentence as FBXW7 in open-access papers (continued):
Sharing a sentence is not in itself a finding about the gene and the disease.
leukemia (36 papers, 2010 to 2025). A malignant (clonal) hematologic disorder, involving hematopoietic stem cells and characterized by the presence of primitive or atypical myeloid or lymphoid cells in the bone marrow and the blood. "In a mouse model of CML, ablation of Fbxw7 induced long-term stem cells to enter the cell cycle, and Fbxw7-deficient leukemia stem cells were sensitized to Ara-C and imatinib." (PMID 35111082, 2021). "The mutated Fbxw7 can activate c-Myc, a protein thought to be connected with Notch1, which, in turn, activates a group of genes necessary for the transformation to leukemia." (PMID 34769401, 2021). "Many NOTCH1 and FBXW7 mutations observed in the primary leukemias were also present in the relapse samples." (PMID 33225950, 2020). "As a substrate of FBXW7-dependent ubiquitination and proteolysis, the Notch signaling pathway has significant influences on cellular differentiation, proliferation, and apoptosis, while the dysregulated Notch signaling is also linked to oncogenesis of both solid tumors and leukemias." (PMID 35515121, 2022). "The Fbxw7 mediate decrease in proliferation, survival and maintenance of leukemia-initiating and leukemia stem cells (LIC/LSC)." (PMID 34372899, 2021). "FBXW7 overexpression can rescue Wnt-induced sensitization to asparaginase in FBXW7 mutant or wild-type leukaemias." (PMID 33935743, 2021). "Mutations in IL7R, FBXW7, and NOTCH1 were specific to myeloid-T MPAL and T-ALL, suggesting a strong functional role of these genes in T cell lineage leukemia." (PMID 29991687, 2018). "In particular, FBXW7 plays a pivotal role in maintaining quiescence in the small pool of leukemia‐initiating cells by mediating c‐Myc degradation." (PMID 26832397, 2016). "Through a CGH array analysis, we next extracted five candidate genes (GALNT2, DCHS2, ENTPD8, PNPLA7, FBXW7) involved in drug resistance in leukemia cells." (PMID 28025493, 2016). "In a T-ALL mouse model, MYC protein levels in leukemia-initiating cells were found to be heavily dependent on FBXW7 activity, demonstrating that MYC is the major contributor to the FBXW7 phenotype." (PMID 25669969, 2015). "Comprehensive profiling of TSPAN32 expression across genetically annotated patient cohorts will be necessary to delineate the precise relationship between leukemia subtype, underlying mutations (e.g., NOTCH1, FBXW7, PHF6, HOXA cluster abnormalities), and TSPAN32 regulation." (PMID 41007654, 2025). "Moreover, Mettl5 KO promotes leukemia growth by translationally inhibiting F-box and WD repeat domain-containing 7 (Fbxw7), a c-MYC degrader and a key regulator of cell differentiation." (PMID 39497033, 2024). "FBXW7 is one of the F-box proteins, which acts as a tumor suppressor through ubiquitination and inducing the degradation of numerous important transcription factors and proto-onco proteins in numerous human cancer, including leukemia." (PMID 35008940, 2022). "Therefore, combinational therapy of Fbxw7 depletion and anti-cancer drug imatinib attenuated leukemia development not only during treatment but also after discontinuation of medication." (PMID 35582573, 2019). "Down-regulation of FBXW7 expression was also reported in other cancers and leukemias." (PMID 26508446, 2015). "Expression of Fbxw7, a subunit of SCF ubiquitin ligase complex, is essential for regulating the threshold of c-Myc in favor of leukemia-initiating cells in chronic myeloid leukemia." (PMID 34769401, 2021). "Recently, new roles have emerged for FBXW7, a substrate‐targeting subunit of the SCF (Skp1‐Cul1‐Fbox) ubiquitin ligase complex, in leukemia." (PMID 26832397, 2016).
leukemia (continued). "Importantly, expression of the most frequently mutated genes in T cell lymphoma or leukemia (i.e., DNMT3A, TET2, JAK, NOTCH1, CDKN2A, PTEN, and FBXW7) was not altered in miR-H18-BCMA CAR T cells." (PMID 35821635, 2022). "Another mechanism of c-MYC regulation is through FBXW7 (F-box and WD repeat domain containing 7, E3 ubiquitin protein ligase), which plays a key role in c-MYC protein degradation in a Thr58-dependent manner, and this mechanism has been shown to play a critical role in leukemia-initiating cells." (PMID 27253416, 2016).
ovarian carcinoma (31 papers, 2016 to 2026). A malignant neoplasm originating from the surface ovarian epithelium. "Under the circumstance of hypoxia, HIF-1α is negatively regulated by FBXW7-mediated ubiquitination and proteolysis in human ovarian cancer cells, proposing an underlying direction for energy reprogramming and angiogenesis." (PMID 35515121, 2022). "Recent NGS screening in different types of advanced tumors, including ovarian cancer, highlighted the presence of FBXW7 mutations that occurred in isolation (12%) or, more frequently (88%), with a concomitant aberration in one or two genes." (PMID 31197119, 2019). "Similar results were also observed in ovarian cancer cell lines with naturally occurring F-box and WD repeat domain-containing 7 (FBW7) mutations." (PMID 27259248, 2016). "The FBXW7-vimentin association may represent previously unrecognized pathway with therapeutic relevance in ovarian carcinoma." (PMID 41869454, 2026). "Functional assays revealed that overexpression of FBXW7 inhibited the proliferation and migration of ovarian carcinoma cells, whereas FBXW7 knockdown had the opposite effect." (PMID 41869454, 2026). "It has been reported that lncRNATTN-AS1 can adsorb miR-15b-5p and regulate the expression of FBXW7 in ovarian cancer." (PMID 40534867, 2025). "CircBNC2 has been reported to inhibit ovarian cancer cell proliferation and migration by targeting the miR-223-3p/FBXW7 axis." (PMID 40723526, 2025). "Meanwhile, FBXW7 has been found to be downregulated in ovarian cancer cells in TCGA data, tumor tissues and cell lines as well." (PMID 40002854, 2025). "It has been reported that lncRNA TTN-AS1 can sponge miR-15b-5p and regulate the expression of FBXW7 in ovarian cancer." (PMID 35928868, 2022). "Xu and the colleague revealed that F-box and WD repeat domain-containing 7 (FBW7) suppressed ovarian cancer progression through targeting the m6A binding protein YTH domain family 2 (YTHDF2)." (PMID 34616622, 2021). "For example, F-box and WD repeat domain-containing 7 (FBW7), an E3-ubiquitin ligase, ubiquitinates YTHDF2 and suppresses tumour progression by antagonizing the tumour-promoting effect of YTHDF2 in ovarian cancer." (PMID 36632454, 2023). "These authors also showed that sensitivity to anti-mitotic agents was regulated by FBXW7 through degradation of MCL1 in colon and ovarian cancer cells." (PMID 27409838, 2016). "In addition, knockdown of FBXW7 can weaken the effect of TTN-AS1 upregulation on cell behavior, suggesting that TTN-AS1 exerts its biological behavior by upregulating FBXW7 in ovarian cancer cells." (PMID 40534867, 2025). "Notably, FBXW7 can inactivate β-catenin pathway to influence the expression of VEGF-A, ultimately suppressing angiogenesis of ovarian cancer cells." (PMID 35515121, 2022). "Moreover, knockdown of FBXW7 attenuated the functions of TTN-AS1 upregulation on cell behaviors, suggesting that TTN-AS1 exerts its biological behaviors via upregulating FBXW7 in ovarian cancer cells." (PMID 35928868, 2022).
T-cell acute lymphoblastic leukemia (26 papers, 2010 to 2025). Acute lymphoblastic leukemia of T-cell origin. "It is known that the FBXW7 gene is frequently mutated in acute lymphoblastic T-cell leukemias and the degron motif containing region of NOTCH1—a key substrate of this ubiquitin ligase—is also mutated as an alternative, if FBXW7 remains intact." (PMID 35328741, 2022). "The NOTCH1 signaling pathway is crucial for T-cell development, and NOTCH1 and/or FBXW7 mutations are frequently detected in T-cell acute lymphoblastic leukemia (T-ALL)." (PMID 29029518, 2017). "Mutations in FBXW7 is approximately 6% of all kinds of cancers, the most common of which is T-cell acute lymphoblastic leukemia (T-ALL; 31%)." (PMID 36358773, 2022). "Current research has documented that in T-cell acute lymphoblastic leukemia, FBXW7 deletion results in the upregulation of MCL1, thereby conferring resistance to the BCL2 inhibitor ABT737." (PMID 40169588, 2025). "Consistent with this, Notch-mediated activation of miR-223 represses FBXW7 in T-cell acute lymphoblastic leukemia." (PMID 37047300, 2023). "In T-cell ALL, the three most frequently mutated genes were NOTCH1 (37.5%), FBXW7 (16.6%), and PTEN (6.2%)." (PMID 36362526, 2022). "Several pairs of co-occurring mutations were found: NRAS with SETD, NRAS with PTPN11 in B-cell ALL (p = 0.024 and p = 0.020, respectively), and NOTCH1 with FBXW7 in T-cell ALL (p < 0.001)." (PMID 36362526, 2022). "In hematopoietic malignancies, FBXW7 has been identified as a tumor suppressor for its ability to mediate proto-oncogene protein degradation in T-cell acute lymphoblastic leukemia." (PMID 32175272, 2020). "PTEN gene inactivation by mutation or deletion is common in pediatric T-cell acute lymphoblastic leukemia (T-ALL), but the impact on outcome is unclear, particularly in patients with NOTCH1/FBXW7 mutations." (PMID 26220040, 2016). "In human T-cell acute lymphoblastic leukaemia and lymphoma (T-ALLs) aberrant Notch activity is caused by mutations of NOTCH1 and FBXW7 in more than 50% of patients." (PMID 24357640, 2014). "T-cell acute lymphoblastic leukemia (T-ALL) is a malignant neoplasm associated with mutations in genes NOTCH1 and FBXW7." (PMID 37681873, 2023).
glioblastoma (24 papers, 2007 to 2025). The most malignant astrocytic tumor (WHO grade IV). "As reported, circ-FBXW7 is abundantly expressed in the normal human brain, while it is reduced in clinical malignant glioma patients, and it is positively associated with glioblastoma patient OS." (PMID 31519156, 2019). "The ATPase Thyroid hormone receptor interactor 13 (TRIP13), usually overexpressed in a myriad of human cancers, promotes glioblastoma migration and invasion by decreasing the transcription of FBXW7 and attenuating its inhibitory effects on c-MYC." (PMID 35515121, 2022). "It has been found that in glioblastoma patients, the overexpression of FBXW7-185aa inhibits the proliferation of cancer cells in vivo and in vitro." (PMID 35223470, 2022). "Exosomal miR-25-3p knocks down the F-box and WD repeat domain-containing-7 (FBXW7), a tumor suppressor, leading to glioblastoma cells’ resistance to temozolomide by enhancing the expression of c-Myc and cyclin E, which are known for their oncogenic properties." (PMID 36139487, 2022). "Circ-FBXW7 was downregulated in glioblastoma tissues and correlated with overall survival of glioblastoma patients." (PMID 30999909, 2019). "On the other hand combination of FBXW7 overexpression with chemotherapeutic drug temozolomide notably sensitized the glioblastoma cells to temozolomide via downregulating Aurora B, MCL-1 and Notch-1, thereby signifying its potential as a target for therapy." (PMID 30791487, 2019). "In line with this, in vitro overexpression of FBXW7 in U251 and U373 human glioblastoma cells were found to remarkably inhibit the proliferation, invasion and migration." (PMID 30791487, 2019). "Studies showed that targeted inhibition of overexpressed microRNA-10b (miR-10b) in glioblastoma can lower the activity of miRNA-15/16 thereby, suppressing its direct targets including FBXW7." (PMID 30791487, 2019). "Similarly, in glioblastoma, miR-92b targets FBXW7 and TRIP13 suppresses its transcription, thereby stabilizing oncogenic proteins like c−MYC and driving tumorigenesis." (PMID 40370434, 2025). "FBXW7 facilitates apoptosis of glioblastoma cells through the ubiquitination and proteolysis of histone deacetylase 7 (HDAC7), which localizes to the inner membrane of mitochondria and will be released into and sequestered within the cytoplasm in response to the initiation of apoptotic cascades." (PMID 35515121, 2022). "FBXW7 was already reported as a miR-25-3p target in glioblastoma." (PMID 35295711, 2022). "We previously reported that F-box/WD repeat-containing protein 7(FBXW7) suppressed the stemness and EMT of CCA, and a recent study proposed that FBXW7 expression was inhibited by TRIP13 in glioblastoma, so we further investigated the correlation between FBXW7 and TRIP13 in pCCA progression." (PMID 33648560, 2021). "It has been reported that FBXW7 is implied in various cancers including glioblastoma." (PMID 21114830, 2010). "Moreover, FBXW7 emerges as a relevant survival marker for patients with glioblastoma that warrants further validation in the clinic." (PMID 17326833, 2007). "In this study, we have shown that the expression of FBXW7 is strongly reduced in glioblastoma." (PMID 17326833, 2007). "Our results show that FBXW7 expression is a prognostic marker for patients with glioblastoma." (PMID 17326833, 2007). "Mutations of FBXW7 in brain tumors have not been investigated yet, however the corresponding locus – 4q31.3 – belongs to the most frequently lost portion of chromosome 4 in glioblastoma." (PMID 17326833, 2007). "In glioblastoma multiforme (GBM), G9a can repress Fbxw7 transcription by promoting H3K9 methylation on the Fbxw7 promoter." (PMID 39080807, 2024).
lymphoma (20 papers, 2010 to 2024). A malignant (clonal) proliferation of B- lymphocytes or T- lymphocytes which involves the lymph nodes, bone marrow and/or extranodal sites. "41% of all FBXW7 mutations in our lymphomas occur at the corresponding codon as one of those positions (canine R470, equivalent to human R465)." (PMID 26377837, 2015). "We demonstrate here that the Fbxw7 gene, a commonly mutated gene in a wide range of mouse and human cancers, shows allele-specific deletions in mouse lymphomas and skin tumors." (PMID 22348067, 2012). "Here we demonstrate that a strain-dependent polymorphism in the N-terminus of Fbxw7 causes 100% selectivity in patterns of alleleic loss in mouse lymphomas." (PMID 22348067, 2012). "Quantitative RT-PCR analysis further confirmed decreased mRNA levels of Fbxw7 in lymphoma tissues from Fbw7ΔEC mice." (PMID 38485719, 2024). "Using genotyping, we found that deletion of the Fbxw7 locus was detected in several lymphoid tissues, including mLNs and bone marrow from lymphoma-bearing Fbw7ΔEC mice." (PMID 38485719, 2024). "It was well established that FBXW7 acted as a main ubiquitin ligase for c‐Myc to promote c‐Myc ubiquitination degradation and subsequently lowered its expression in adult T cell leukaemia/lymphomas cells." (PMID 33369138, 2021).
acute lymphoblastic leukemia (19 papers, 2011 to 2025). Leukemia with an acute onset, characterized by the presence of lymphoblasts in the bone marrow and the peripheral blood. "The Group for Research in Adult Acute Lymphoblastic Leukemia (GRAALL) validated in adult T-ALL patients the clinical utility of a new oncogenetic classifier based on the mutational status of NOTCH1/FBXW7/PTEN/RAS (NFPR) genes." (PMID 33614543, 2020). "It is also notable that the clustering of MYB, NOTCH1, RUNX1, and FBXW7 mutations seen in this uncommon epithelial tumor ACC overlaps with frequent somatic mutations seen in human acute lymphocytic leukemia patients." (PMID 25587024, 2014). "Cancer-associated FBXW7 mutations are most frequent in T cell acute lymphoblastic leukemia (T-ALL), followed by precursor T cell lymphoblastic lymphoma (T-LBL), endometrial carcinoma, small intestine carcinoma, and large intestine carcinoma." (PMID 32429232, 2020). "For instance, Notch1 mutations occur in over 50% of both pediatric and adult T-cell acute lymphoblastic leukemia (T-ALL) cases, while Fbxw7 mutations are found in up to 20% of T-ALL cases." (PMID 28149836, 2016). "In acute lymphoblastic leukemia, miR-223-3p mediated by the Notch pathway inhibits the E3 ligase FBXW7 expression." (PMID 38105184, 2023). "Deletion of FBXW7 or its functional inactivation in acute lymphoblastic leukemia (ALL) cells, impairs MCL1 degradation in response to DNA-damaging agents, resulting in MCL1 overexpression and evasion of apoptosis." (PMID 35345853, 2022). "In acute lymphoblastic leukemia, FBXW7 mediates VDAC3 ubiquitination, resulting in ferroptosis." (PMID 41268533, 2025). "MYC-translocated T-lineage acute lymphoblastic leukemia (T-ALL) is a rare subgroup of T-ALL associated with CDKN2A/B deletions, PTEN inactivation, and absence of NOTCH1 or FBXW7 mutations." (PMID 30304769, 2018).